RN7SKP51 (RN7SK pseudogene 51)
Gene: Miscellaneous RNA gene on chromosome 6 (117,301,455 to 117,301,758, forward strand). Ensembl gene ENSG00000222713.
Homologues: Orthologues: chimpanzee 7SK (99% identical). Paralogues in human: RN7SKP18 (73% identical), RN7SKP294 (66% identical), RN7SKP124 (64% identical), RN7SKP77 (64% identical), RN7SKP217 (63% identical), RN7SKP240 (63% identical), RN7SKP127 (63% identical), RN7SKP184 (63% identical), RN7SKP146 (62% identical), RN7SKP79 (62% identical), RN7SKP86 (62% identical), RN7SKP230 (62% identical), and 284 more.